EGFR (epidermal growth factor receptor)
Diseases named in the same sentence as EGFR in open-access papers (continued):
Sharing a sentence is not in itself a finding about the gene and the disease.
lung cancer (continued). "This study provides specifc data for the study of EGFR mutations in lung cancer research and treatment." (PMID 25013503, 2014). "Although such assumptions are valid for some recurrent mutations such as the L858R mutation in epidermal growth factor receptor (EGFR) in lung cancer and V600E in BRAF in melanoma, there is emerging evidence that rare mutations can be drivers." (PMID 24743239, 2014). "We found that EGF was involved in the development of the lung cancer inflammatory microenvironment through the over-production of CXCL8 associated with the activation of EGFR pathway." (PMID 24629040, 2014). "57.7% of EGFR-associated lung cancers were adenocarcinomas and 86.7% of EGFR mutations associated with ‘high differentiation’ cancers." (PMID 24760004, 2014). "All 23 patients with lung cancer with mutated EGFR DNA in the pretreatment blood sample ultimately developed disease progression during treatment with erlotinib." (PMID 25103305, 2014). "Tyrosine kinase inhibitors (TKI) have changed advanced EGFR mutated lung carcinoma clinical practice with global improved short-term survival and fewer side effects." (PMID 24885034, 2014). "Single-agent EGFR inhibitor therapy is effective mainly in patients with lung cancer and EGFR mutations." (PMID 23800712, 2013). "Many attempts have been made to overcome the resistance of lung cancers refractory to reversible EGFR-TKIs and harboring EGFR activating mutations." (PMID 24386407, 2013). "Although rarer than lung cancer with EGFR mutation, the identification of kinase gene fusions, including EML4-ALK, in lung cancer leads to molecularly-targeted therapy with kinase inhibitors." (PMID 23617234, 2013). "There is only one study reported from India on EGFR mutations in lung cancer, which focuses mainly on the epidemiology of patients who harbor these mutations." (PMID 23620765, 2013). "Numerous studies reported Resv-associated inhibition of constitutively enhanced EGFR phosphorylation in prostate, colon, lung cancer, and breast cancer cell lines." (PMID 23527233, 2013). "We have therefore evaluated the efficacy and feasibility of combinations of crizotinib and new generation EGFR inhibitors in overcoming the resistance to EGFR-TKIs of lung cancer cells harboring EGFR mutations." (PMID 24386407, 2013). "The study included 76 surgically-removed lung cancer cases from patients of the Nagoya City University Hospital in which the EGFR and NFE2L2 mutation status was already established." (PMID 24137397, 2013). "There was one case report that described a patient with a thyroid metastasis from lung cancer with an epidermal growth factor receptor (EGFR) mutation, and the patient was started on erlotinib and had a marked response in the lung and thyroid mass." (PMID 24455357, 2013). "Lung cancers with mutations that activate epidermal growth factor receptor (EGFR), including exon 19 deletions and the exon 21 L858R point mutation, respond to the reversible EGFR-tyrosine kinase inhibitors (EGFR-TKIs) gefitinib and erlotinib." (PMID 24386407, 2013). "Because EGFR-mutated lung cancers are dependent on mutant EGFR, the EGFR tyrosine kinase inhibitors (TKIs) show promising therapeutic efficacy in patients with EGFR-activating mutations, such as exon 19 deletions and L858R point mutations." (PMID 23533466, 2013). "This demonstrates that the EGFR mutations are tumor-specific, and likely an initiating event in lung cancer tumorigenesis." (PMID 23419122, 2013). "Another novel irreversible pan-HER inhibitor HM781-36B has recently shown promise in the inhibition of EGFR, HER2, and HER4 as well as against the gatekeeper mutation – EGFR T790M that is responsible for acquired drug resistance in lung cancer patients." (PMID 23407898, 2013). "Since then, EGFR mutation has become an important biomarker in lung cancer screening as identifying this biomarker can predict which patient will benefit from EGFR targeted therapy." (PMID 23590575, 2013).
lung cancer (continued). "Around 50–60% of Asian patients and 20–30% of Western patients with adenocarcinomas are expected to carry activating EGFR mutations, while a negligible proportion of patients with other lung cancer histology are expected to carry such mutations." (PMID 23927790, 2013). "If increases as a result of mutations in EGFR, we expect an increase in miR-9 and a decrease in let-7 as indeed are observed in lung cancer." (PMID 23365639, 2013). "Despite this, published data concerning the EGFR mutation status of metastatic tumours and corresponding primary lung cancers are limited, particularly in the Caucasian population." (PMID 23892415, 2013). "To confirm the efficiency of Method A in FFPE tissue specimens, we analyzed the EGFR mutation in different amounts of FFPE human lung cancer tissue using the PyroMark ID System." (PMID 23691506, 2013). "The era of molecular targeted therapy in lung cancer had its origin in 2004, when activating mutations in the epidermal growth factor receptor (EGFR) and their correlation with clinical response to EGFR tyrosine kinase inhibitors (TKIs) were discovered." (PMID 23802096, 2013). "EGFR has been implicated in the growth of several human epithelial malignancies, including lung cancer." (PMID 23407898, 2013). "In clinical studies, gefitinib induces initial tumor regressions in lung cancer patients with EGFR activating mutations, including Exon19 Del, L858R mutation, and has no significant anti-tumor activity in lung cancer patients with KRAS mutation." (PMID 23842453, 2013). "In primary non–small cell lung cancer that harbors EGFR mutations, multiple randomized clinical trials comparing first-line chemotherapy to EGFR tyrosine kinase inhibitors (TKIs) have been performed and uniformly demonstrated the superiority of EGFR-TKIs." (PMID 24205362, 2013). "We further tested the reliance of EGFR-mutated lung cancer cells on the core network by determining how known resistance mechanisms to EGFR TKI perturb the dependency of cells on the core network." (PMID 24189400, 2013). "Gefitinib greatly enhanced NK cell cytotoxicity to lung cancer cells with EGFR L858R + T790M resistance mutation." (PMID 23937717, 2013). "Among the 24 drugs, 3 were designed to directly target EGFR, whose association with lung cancer has been widely reported." (PMID 24369726, 2013). "BEAMing successfully quantified APC and KRAS mutations in the ctDNA of colorectal cancer patients and EGFR mutations in the ctDNA of lung cancer patients." (PMID 24278442, 2013). "Lung cancers that harbor somatic activating mutations in the gene for EGFR depend on mutant EGFR for their proliferation and survival; therefore, lung cancer patients with EGFR mutation often dramatically respond to orally available EGFR-TKIs." (PMID 23533466, 2013). "In this article, we review the four commonly known oncogenic driver mutations in lung cancer – EGFR mutations at exons 18 – 21, KRAS gene mutation at codons 12 and 13, EML4-ALK fusion genes and deregulation of MET signaling." (PMID 27234388, 2013). "Gefitinib, an EGFR tyrosine-kinase inhibitors, has shown a high response rate in the treatment of lung cancer in patients with EGFR mutation." (PMID 23425899, 2013). "The functional relevance of restoration of NKG2D–NKG2DL interaction by gefitinib was demonstrated by the enhanced cytotoxicity, degranulation and IFN-γ production of NK cells in response to lung cancer cells with EGFR L858R + T790M resistance mutation." (PMID 23937717, 2013). "MPR expression-induced by gefitinib can facilitate NK cell cytotoxicity in human lung cancer cells with EGFR L858R + T790M resistance mutation." (PMID 23937717, 2013).
lung cancer (continued). "Here, we describe an EGFR interactome of 263 proteins and offer a 14-protein core network critical to the viability of multiple EGFR-mutated lung cancer cells." (PMID 24189400, 2013). "Our findings support the proposal that icotinib inhibits the proliferation of human lung cancer cells with EGFR mutations by inducing cell cycle arrest and cell death." (PMID 23586056, 2013). "These mutations increase the susceptibility to EGFR-TKIs activity but all the EGFR-mutant lung cancer patients experience disease progression within 10 to 14 months from the beginning of the therapy." (PMID 24167634, 2013). "Epidermal growth factor receptor tyrosine kinase inhibitors (EGFR-TKIs) has shown a high response rate in the treatment of lung cancer in patients with (EGFR) mutation." (PMID 23769345, 2013). "The recent success in suppressing the growth of cultured lung cancer cells with activating EGFR mutations by siRNA unveiled the sensitivity of siRNA-based approaches in distinguishing drivers of tumour growth." (PMID 23666744, 2013). "For example, we and other researchers reported that HGF overexpression can exist together with gatekeeper EGFR-T790M mutation or Met gene amplification in EGFR mutant lung cancer with acquired resistance to EGFR-TKIs." (PMID 24386407, 2013). "Several other studies, although different in certain aspects from the present study of germline -216G/T variants, have also documented the associations of somatic mutations in EGFR with pleural metastasis of lung cancer." (PMID 24137392, 2013). "Direct sequencing remains the most widely used method for the detection of epidermal growth factor receptor (EGFR) mutations in lung cancer; however, its relatively low sensitivity limits its clinical use." (PMID 24376508, 2013). "Gefitinib and erlotinib are orally administered epidermal growth factor receptor (EGFR) tyrosine kinase inhibitors (TKIs) used for the treatment of non–small-cell lung cancer (NSCLC) in patients with activated mutations of the EGFR gene." (PMID 23566546, 2013). "We detected epidermal growth factor receptor (EGFR) mutations in the plasma DNA of lung cancer patients." (PMID 24278442, 2013). "MET amplification in lung cancer has recently been shown to be associated with activation of EGFR, ERBB2, ERBB3, and RET." (PMID 23300999, 2013). "Overall, our findings suggest that patients with advanced lung cancer harbored marked EGFR mutational heterogeneity." (PMID 23418425, 2013). "Lung cancer cell lines made resistant to EGFR-TKIs by the gatekeeper EGFR-T790M mutation, Met amplification, and HGF overexpression and mice with tumors induced by these cells were treated with crizotinib and a new generation EGFR-TKI." (PMID 24386407, 2013). "We used A549 (lung cancer cells with endogenous EGFR-WT) and H1975 (lung cancer cells with endogenous mutated EGFR-L858R-T790M) to monitor them." (PMID 23520446, 2013). "There are several studies evaluating the presence of EGFR mutations in CNS lung cancer metastases in the Asian population." (PMID 23892415, 2013). "A biological and genetical variation of lung cancer is NSCLC which bears activating mutations in the tyrosine kinase domain of the epidermal growth factor receptor (EGFR)." (PMID 23423475, 2013). "We also targeted the EGFR L858R mutation in a set of nine surgical FFPE lung cancer specimens in which eight were known to be positive." (PMID 24280411, 2013). "Another preclinical study demonstrated that irradiation activates the EGFR by releasing transforming growth factor α, whereas the effect of EGFR-TKIs on lung cancer was proven to be dependent on EGFR mutations." (PMID 24649230, 2013).
lung cancer (continued). "EGFR mutations, which are mostly limited to the first four exons, occur more often in lung cancer patients with adenocarcinoma histology, Asian origin, female gender and a non-smoking background." (PMID 24137392, 2013). "Selection of lung cancer patients for therapy with tyrosine kinase inhibitors directed at EGFR requires the identification of specific EGFR mutations." (PMID 24376723, 2013). "One lung cancer case was positive for the activating EGFR mutation G719C, as well as the EGFR S768I mutation that is associated with resistance to anti-EGFR therapy." (PMID 24280411, 2013). "These genetic aberrations were thought to be susceptible to either EGFR-TKIs or EGFR-blocking monoclonal antibody therapy in primary non–small cell lung cancer or in recurrent glioblastoma." (PMID 24205362, 2013). "The presence of an EML4-ALK translocation with concomitant EGFR/KRAS mutations is very rare among lung cancer patients." (PMID 23341890, 2013). "In NSCLC cell lines, HDAC inhibition leads to Hsp90 acetylation, depletion of EGFR, and other key survival signaling proteins, and triggers apoptosis only in lung cancer cells harboring EGFR mutations." (PMID 24130964, 2013). "Approximately 15% of tumors in lung cancer patients exhibit EGFR activating mutations and have significant responses to TKIs targeting EGFR." (PMID 23866081, 2013). "ErbB1 gene mutations and amplification usually occur together, and lung cancer cell lines that manifest both events exhibit high levels of EGFR." (PMID 23631593, 2013). "One study reported that the rate of somatic mutations in EGFR was significantly higher in lung cancer patients with pleural metastasis compared with patients without metastasis (68.4 vs. 50.5%)." (PMID 24137392, 2013). "Studies with erlotinib show increased survival in unselected patients with lung cancer, though there is a general consensus that patients with sensitive EGFR mutations are most likely to benefit." (PMID 23800712, 2013). "Although the survival rate has been improved since the introduction of third-generation anti-neoplastic agents and epidermal growth factor receptor (EGFR) tyrosine kinase inhibitors, lung cancer is still the leading cause of cancer deaths in the world." (PMID 23840757, 2013). "Recent clinical trials have shown that first-line treatment for EGFR-mutated lung cancers with EGFR-TKIs induced much higher response rates and longer progression-free survival than platinum-based chemotherapies." (PMID 23533466, 2013). "In this report, we established a method of detecting EGFR mutations in ctDNA in the peripheral blood of lung cancer patients using single-pass deep sequencing of amplified EGFR fragments." (PMID 24278442, 2013). "Mutations in the epidermal growth factor receptor (EGFR) are found in many advanced lung cancer patients who respond positively to EGFR tyrosine kinase inhibitors, gefitinib or erlotinib." (PMID 23805327, 2013). "PIK3CA mutations have been detected in about 5% of EGFR-mutant lung cancers with acquired resistance to EGFR-TKI therapy." (PMID 23936763, 2013). "They detected EGFR mutations in lung cancer samples using both direct DNA sequencing and the sensitive ARMS technique." (PMID 23934203, 2013). "Lung cancers that depend on mutated EGFR constitute one of the biggest lung cancer subsets characterized by molecular aberrations, accounting for ~50% in East Asians and ~15% in Caucasians." (PMID 23533466, 2013). "Several previous studies have reported prolongation of the survival time in patients with EGFR-mutation-positive lung carcinomas treated with EGFR-tyrosine kinase inhibitors (TKIs), therefore, EGFR-TKIs are widely used in medical practice." (PMID 23879483, 2013). "Targeted NGS is robust, cost-effective and greatly improves the detection of EGFR mutations in lung carcinoma patients." (PMID 24376723, 2013).
lung cancer (continued). "Discovery of EGFR-TKIs which is based on the novel understanding of biological mechanisms underlying lung cancer development is a breakthrough in the therapeutic strategy of thoracic oncology." (PMID 22489192, 2012). "Met amplification has been associated with acquired EGFR TKI resistance in lung cancer cell lines and human lung tumors containing EGFR tyrosine kinase domain mutations." (PMID 22788954, 2012). "The majority of human lung cancers are adenocarcinomas carrying somatic mutations in the genes that encode the EGFR/KRAS/BRAF pathway." (PMID 22654667, 2012). "The R1275Q mutation of ALK is correspondingly adjacent to the most common lung cancer-associated mutation (L858R) in EGFR." (PMID 22347506, 2012). "Collectively our results suggest the existence of a cooperative effect between EGF pathway activation and TWIST1 reactivation in promoting EMT in EGFR mutated lung cancer." (PMID 22272264, 2012). "Unfortunately, lung cancers with drug sensitive EGFR mutations that initially respond to gefitinib or erlotinib eventually develop acquired resistance from between six months to two years later." (PMID 22928112, 2012). "EGFR mutations have been widely reported in lung cancer by many researchers and play a key role in lung cancer therapy." (PMID 26316937, 2012). "In our model, we confirmed that EGF-driven EMT was reversible in EGFR mutated TWIST1 expressing lung cancer cells." (PMID 22272264, 2012). "Our findings demonstrated, for the first time, that CARMA3 was overexpressed in NSCLC and correlated with lung cancer progression, EGFR expression, and EGFR mutation." (PMID 22615840, 2012). "Approximately 50% of patients with EGFR mutant lung cancers who develop acquired resistance to EGFR TKIs have a second-site mutation T790M in the threonine gatekeeper residue that coexists with a primary EGFR activating mutation." (PMID 22970367, 2012). "Epidermal growth factor receptor (EGFR) overexpression and mutations were existed in more than 40% of the lung cancer, and it's the one of molecular targets in clinical treatment." (PMID 23249714, 2012). "In clinical studies of metastatic colon cancer, patients with wild type K-ras, B-raf and PIK3CA genes gain benefit from cetuximab therapy, whilst lung cancer patients with mutations in exons 19 and 21 of the EGFR gene benefit from Iressa or Tarceva therapy." (PMID 22935382, 2012). "In lung cancer, EGFR mutations cluster in exons 18 to 21, encoding the domain of the tyrosine kinase that contains the ATP binding pocket." (PMID 23244191, 2012). "Activating EGFR mutations, such as delE746-A750 and L858R, cause lung cancer cells closely couple EGFR with cell proliferation or survival." (PMID 22815900, 2012). "To validate that TWIST1 is a driver of EMT in EGFR mutated lung cancer, we used five human lung cancer cell lines and demonstrated that EMT and the associated cell mobility were dependent upon TWIST1 expression in cells with EGFR mutation." (PMID 22272264, 2012). "Recently, the addition of cetuximab to afatinib has yielded impressive results in the treatment of EGFR reversible TKI resistant lung cancer due to T790M mutation." (PMID 22436374, 2012). "The aim of this study was to investigate the possible implication of TWIST1 reactivation on the acquisition of a mesenchymal phenotype in EGFR mutated lung cancer." (PMID 22272264, 2012). "Therapeutic agents targeting the EGFR signaling pathway, including two EGFR kinase inhibitors gefitinib and erlotinib, are clinically effective in treating lung cancer patients harboring these EGFR activating mutations." (PMID 22970367, 2012). "The EGFR mutations in lung cancer associated with sensitivity to EGFR-TKIs occur more frequently in women, nonsmokers, Asians, and with adenocarcinomas." (PMID 22784503, 2012). "MET amplification was also observed at a low frequency in EGFR mutant lung cancers in patients prior to treatment and was associated with the development of acquired resistance to EGFR TKIs." (PMID 22970367, 2012).